TMEFF2 (transmembrane protein with EGF like and two follistatin like domains 2)
Diseases named in the same sentence as TMEFF2 in open-access papers (continued):
Sharing a sentence is not in itself a finding about the gene and the disease.
glioma (5 papers, 2011 to 2022). A benign or malignant brain and spinal cord tumor that arises from glial cells (astrocytes, oligodendrocytes, ependymal cells). "One study found that methylation of the TMEFF2 promoter region was associated with poor outcomes in patients with glioma, a type of brain tumour." (PMID 35052446, 2022). "TMEFF2 overexpression also caused a marked decrease in proliferation of AtT20 human glioma cells when tested through both short-term (WST-1 assay) and long-term (soft agar colony formation) cell proliferation assays." (PMID 33371267, 2020). "Our results suggest that TMEFF2 DNA methylation might be associated with glioma tumour progression and could serve as a valuable prognostic marker for adult diffuse gliomas." (PMID 33663520, 2021). "Additionally, survival analysis of TMEFF2 expression in primary gliomas implicated high expression of TMEFF2 in better overall survival than low expression (HR = 0.21, P < 0.001)." (PMID 33663520, 2021). "To further interrogate the methylation sites of TMEFF2 in glioma, we identified 49 differentially methylated cytosines (DMCs) in a total of 73 CpG sites in the TMEFF2 promoter that were hypermethylated in glioblastoma cells compared to SVG p12 cells." (PMID 33663520, 2021). "In this study, we attempted to investigate TMEFF2 expression and promoter methylation in primary glioma tissue samples and in vitro cultured glioblastoma cells." (PMID 33663520, 2021). "In our cohort, TMEFF2 promoter methylation was found to increase with glioma tumour grade; inversely, its mRNA expression was reduced from low- to high-grade glioma." (PMID 33663520, 2021). "In this study, we assessed TMEFF2 promoter methylation and expression in glioma and highlighted the clinical significance of TMEFF2 methylation in glioma." (PMID 33663520, 2021). "To determine the correlation between TMEFF2 promoter methylation and overall survival (OS) in glioma patients, we initially performed Kaplan-Meier survival curves with a log-rank test based on the best separation model." (PMID 33663520, 2021). "In our current study, we confirmed that compared to that in healthy tissue, TMEFF2 expression is significantly decreased in glioma tumour tissues and GBM cells." (PMID 33663520, 2021). "IDH1 mutant glioma tissues (n = 23) harboured lower TMEFF2 methylation levels than IDH1 wild-type glioma tissues (n = 20) (P < 0.05)." (PMID 33663520, 2021). "To further explore the correlation between TMEFF2 methylation and adult diffuse glioma, we combined the Brain Low Grade Glioma and Glioblastoma Multiforme datasets from TCGA and generated a pan-glioma cohort with 1122 primary glioma samples." (PMID 33663520, 2021). "After evaluating immunostained paired tumour and peritumoural specimens from 75 glioma patients and normal brain specimens from 5 epilepsy patients, we observed a relatively low level of TMEFF2 protein expression in 70.67 % (53/75) of all tumour specimens." (PMID 33663520, 2021). "RT-PCR of 23 paired glioma samples showed that TMEFF2 mRNA expression levels were lower in tumour tissues than in peritumour tissues (P < 0.01)." (PMID 33663520, 2021).
glioma (continued). "In our study, we observed a small subset (27/427) of IDH1 mutant gliomas with a high degree of TMEFF2 methylation that exhibited a poor prognosis compared to the large subset (400/427), which had less TMEFF2 methylation." (PMID 33663520, 2021). "Owing to the previously reported ectodomain shedding of TMEFF2 upon treatment of A172 glioma cells with TNFα and interleukin-1, Knauper’s group investigated TMEFF2 as a substrate of ADAM proteases." (PMID 33371267, 2020). "TMEFF2 is downregulated in glioma and cotricotropinomas, and it impairs the production of adrenocorticotropic hormone in glioma cells." (PMID 33371267, 2020). "To identify changes in methylation of the TMEFF2 promoter in glioma, we performed bisulfite amplicon sequencing (BSAS) in 1 patient-derived primary glioblastoma cell line (NFHDCD) and 3 glioblastoma cell lines (T98G, LN229, and U87MG), and we also analysed a normal astroglial cell line (SVG p12)." (PMID 33663520, 2021). "Taken together, these results indicate that low TMEFF2 expression in gliomas may be due to methylation regulation of its promoter." (PMID 33663520, 2021). "In this study, we investigated TMEFF2 expression in surgical glioma tissue samples." (PMID 33663520, 2021). "However, more detailed studies need to be performed to better understand the regulatory mechanism of TMEFF2 promoter methylation and transcription in gliomas." (PMID 33663520, 2021). "In addition, using data of TCGA GBM and LGG cohorts, we ascertained that TMEFF2 expression is progressively downregulated during the progression from Grade II to Grade IV glioma." (PMID 33663520, 2021). "Due to tumour heterogeneity among glioma patients, TMEFF2 methylation may be a biomarker of poor prognosis in IDH1 mutant glioma patients." (PMID 33663520, 2021). "Given that adult diffuse gliomas are highly heterogeneous, we hypothesized that TMEFF2 promoter methylation was correlated with one of the glioma subtypes." (PMID 33663520, 2021). "Moreover, we explored the prognostic significance of TMEFF2 in gliomas by analysing a cohort dataset from TCGA." (PMID 33663520, 2021). "Although TMEFF2 promoter methylation levels vary in different adult glioblastoma subtypes in The Cancer Genome Atlas (TCGA) database, its expression and promoter methylation in glioma cells remain unconfirmed." (PMID 33663520, 2021). "Likewise, not only was TMEFF2 expression downregulated in glioma but also its mRNA levels decreased with increasing grade and worsening treatment outcomes." (PMID 33371267, 2020). "Furthermore, studies using limited numbers of clinical samples, reveal changes in the expression of Tmeff2 with disease stage in PCa and gliomas, supporting an important role of Tmeff2 in these diseases." (PMID 31060542, 2019). "In addition, we show for thefirst time that the expression of TMEFF2 is downregulated in glioma and severalother cancers and that this downregulation correlates with DNA methylation." (PMID 21559523, 2011). "To confirm the correlation between TMEFF2 promoter methylation and expression in gliomas, we queried a dataset from TCGA and observed a significant negative correlation (Spearman’s r = – 0.47, P < 0.001) between the TMEFF2 promoter methylation level and mRNA expression in glioma." (PMID 33663520, 2021). "Downregulation of TMEFF2 may be related to glioma tumour progression." (PMID 33663520, 2021). "Thus, methylated TMEFF2 DNA could also be a used as a detectable indicator in glioma patients’ tumour specimens or cerebrospinal fluid in the future." (PMID 33663520, 2021).
glioma (continued). "Furthermore, TMEFF2 inhibited the production of adrenocorticotropic hormone (ACTH) in response to CRH (corticotropin releasing hormone) stimulation in AtT20 glioma cells; this action was demonstrated to be the result of TMEFF2-imparted action at multiple levels of CRHR1 signalling." (PMID 33371267, 2020). "Since themethylation status of TMEFF2 has not been reported in glioma and most othertissues, we analyzed all publicly available data from The Cancer Genome Atlas(TCGA) with results on both Agilent expression and Infinium methylation arrays." (PMID 21559523, 2011). "However, we failed to clarify TMEFF2 expression in glioma tumour tissues or cells by Western blot (WB) using commercial antibodies (data not shown)." (PMID 33663520, 2021). "We have found that TMEFF2 hypermethylation is associated with non-Proneural subtypesof GBMs, in contrast with G-CIMP methylation and IDH1 mutation status, which areassociated with the Proneural subtype and lower-grade gliomas." (PMID 21559523, 2011).
bladder cancer (4 papers, 2015 to 2025). "TMEFF2 has been identified as an epigenetic biomarker for bladder cancer, showing significant associations with increasing tumor grade and stage." (PMID 39513726, 2024). "Costa reported that Vim could associate with GDF15 and TMEFF2 to predict bladder cancer." (PMID 25907256, 2015). "Moreover, TMEFF2 is a crucial biomarker for predicting bladder cancer through DNA‐based analyses of urine samples." (PMID 39980308, 2025). "al. showed three novel gene loci, i.e., GDF15, TMEFF2, and VIM, whose DNA methylation could be suitable for detecting bladder cancers in urine samples." (PMID 32046186, 2020).
lung carcinoma (4 papers, 2013 to 2023). "The methylation of TMEFF2 was identified in tissues from lung cancer patients, associated with reduced TMEFF2 expression level." (PMID 36672944, 2023). "Lung cancer-specific cDMCs were found at the promoters of SH3GL3, IGF2, and TMEFF2." (PMID 28751909, 2017).
breast carcinoma (3 papers, 2011 to 2020). "TMEFF2 had previously been reported to be methylated in lung adenocarcinoma, and inactivation of DNA methyltransferase 1 in a breast cancer cell line reactivates methylated TMEFF2, suggesting its DNA methylation leads to silencing." (PMID 21731750, 2011). "In breast cancer, TMEFF2 promoter methylation increases progressively along the potential developmental path of invasive ductal carcinoma (IDC) from the preinvasive lesions like flat epithelial atypia (FEA), atypical ductal hyperplasia (ADH) and ductal carcinoma in situ (DCIS)." (PMID 33371267, 2020). "In a small cohort of 110 tumours and 21 normal breast tissue samples, the TMEFF2 promoter was found to be hypermethylated in recurrent breast cancer compared to non-recurrent cancer (and normal breast tissue)." (PMID 33371267, 2020).
colorectal cancer (3 papers, 2014 to 2020). A primary or metastatic malignant neoplasm that affects the colon or rectum. "In the case of ulcerative colitis-associated colorectal cancer, TMEFF2 methylation was observed in 40% of dysplasia and 50% of carcinomas, but no methylation was detected in the non-neoplastic mucosae." (PMID 33371267, 2020). "TMEFF2 is methylated early during oncogenesis in breast and colorectal cancer, and the detection of methylated free-circulating TMEFF2 DNA has been suggested as a potential diagnostic tool." (PMID 33371267, 2020). "Further corroborating evidence on the onco-suppressive role of TMEFF2 came from studies in gastric and colorectal cancers." (PMID 33371267, 2020). "Recognizing that abnormally methylated DNA correlated with the presence of colorectal cancer, He and colleagues developed a polymerase chain reaction (PCR) assay to detect the mutation status of several colorectal cancer selected genes (mSEPT9, ALX, TMEFF2) called the MethyLight assay." (PMID 30128304, 2018). "Methylation of three of these genes, SEPT9, TMEFF2 and ADAMTS1 has been previously reported in colorectal cancer and they show partial or high level methylation in 10, 10 and 7 cancer DNAs, respectively." (PMID 24485021, 2014).
endometrial cancer (3 papers, 2020 to 2024). Primary or metastatic malignant neoplasm involving the endometrium (mucous membrane that lines the endometrial cavity). "TMEFF2 was highly expressed in endometrial cancer tissues, and its high expression was associated with the FIGO stage, degree of differentiation, and lymph node metastasis." (PMID 39518001, 2024). "The data from this research indicate that the expression of TMEFF2 is associated with the development and progression, as well as the prognosis, of endometrial cancer, and may also assist in identifying therapeutic targets for the endometrium." (PMID 39518001, 2024). "The expression of TMEFF2 was also determined in three lines of endometrial cancer cells (Ishikawa, HEC-1A, and HEC-1B)." (PMID 39518001, 2024). "The univariate Kaplan–Meier analysis showed that the overall recurrence-free survival was significantly lower in patients with endometrial cancer with a high TMEFF2 expression compared to patients with a low TMEFF2 expression (p = 0.015)." (PMID 39518001, 2024). "A total of 75 cases of endometrial cancer were divided into groups with low (-/+) and high (++/+++) expressions of TMEFF2 based on the TMEFF2 expression in endometrial cancer tissues." (PMID 39518001, 2024). "Several studies have been conducted on TMEFF2 in the oncological diseases of the female reproductive system, focusing on the methylation of TMEFF2 in endometrial cancer, high-grade squamous intraepithelial lesions (HSIL), and cervical cancer." (PMID 39518001, 2024). "Conversely, TMEFF2 was reported to exhibit oncogenic properties in endometrial carcinoma (EC), where its expression increased gradually through clinical stages, nodal metastasis and de-differentiation of endometrial tissue." (PMID 33371267, 2020). "Then, in order to identify the targets of TMEFF2 in endometrial cancer, GSEA was performed." (PMID 35163161, 2022). "In addition, knocking down TMEFF2 in endometrial carcinoma cells (Ishikawa) resulted in reduced cell proliferation, invasion and migration, inhibition of MAPK and PI3K-AKT pathways, and downregulation of the signature proteins of epithelial to mesenchymal transition (EMT)." (PMID 33371267, 2020). "Expression of TMEFF2 and BTG anti-proliferation factor 1 (BTG1) was lower in primary endometrial cancer compared to the healthy endometrium, while significant overexpression was noted for ring finger protein 183 (RNF183)." (PMID 35163161, 2022). "It was observed that TMEFF2 expression was increased in endometrial cancer, and its silencing inhibited EMT and the activation of MAPK and PI3K pathways, which suggest that TMEFF2 can help diagnose and treat endometrial cancer." (PMID 35163161, 2022).
glioblastoma (3 papers, 2011 to 2021). The most malignant astrocytic tumor (WHO grade IV). "TMEFF2 promoter methylation levels were increased in glioblastoma cells compared with SVG p12 cells (P < 0.001)." (PMID 33663520, 2021). "Conversely, RT-PCR demonstrated that the TMEFF2 mRNA expression was lower in glioblastoma cells than in the other cells tested." (PMID 33663520, 2021). "Methylation-specific PCR (MSP) verified TMEFF2 promoter hypermethylation in glioblastoma cells." (PMID 33663520, 2021). "TMEFF2 expression is downregulated inhuman brain cancers and is negatively correlated with PDGF-AA expression.Suppressed expression of TMEFF2 is associated with its hypermethylation inseveral human tumor types, including glioblastoma and cancers of ovarian,rectal, colon and lung origins." (PMID 21559523, 2011). "To verify the biological function of the TMEFF2 protein in glioblastoma cells, we examined the effects of TMEFF2 knockdown by two distinct siRNAs on the glioblastoma cell line U87MG and the primary glioblastoma cell line NFHDCD." (PMID 33663520, 2021). "Knockdown of TMEFF2 in both U87MG and NFHDCD glioblastoma cells significantly increased the ratio of EdU + cells as demonstrated by EdU tests, and knockdown promoted cell proliferation, as demonstrated by CCK8 tests." (PMID 33663520, 2021). "In addition, we conducted bisulfite amplicon sequencing (BSAS) and methylation-specific PCR (MSP) to evaluate TMEFF2 methylation in glioblastoma (GBM) cells." (PMID 33663520, 2021).
non-small cell lung carcinoma (3 papers, 2017 to 2021). A group of at least three distinct histological types of lung cancer, including non-small cell squamous cell carcinoma, adenocarcinoma, and large cell carcinoma. "Transmembrane protein with a single EGF-like and two follistatin domains (TMEFF2) is inactivated through promoter methylation in numerous cancers including non-small-cell lung cancer (NSCLC)." (PMID 29038612, 2017). "For instance, miR-323-3p suppressed the expression of transmembrane protein with EGF-like and 2 follistatin domain (TMEFF2) and the activation of AKT and ERK pathways, by which it inhibited the apoptosis in non-small-cell lung cancer (NSCLC) cell lines." (PMID 32478079, 2020).
Alzheimer disease (2 papers, 2020 to 2022). A progressive, neurodegenerative disease characterized by loss of function and death of nerve cells in several areas of the brain leading to loss of cognitive function such as memory and language. "The neuroprotective effect of TMEFF2 has also been found in Alzheimer’s disease as it binds Amyloid-β oligomer and Amyloid-β protein precursor." (PMID 35052446, 2022). "Physiological function of TMEFF2 is elusive; however, the protein is reported to be involved in wide-ranging physiological and pathological functions including neuroprotection in Alzheimer’s diseases, interferon induction and one-carbon metabolism." (PMID 33371267, 2020). "Interestingly, through binding the amyloid β protein, its precursor and derivatives, TMEFF2 provides neuroprotection in Alzheimer’s disease." (PMID 33371267, 2020).
colon adenocarcinoma (2 papers, 2011 to 2021). "TMEFF2 expression is barely detectable inalmost all colon adenocarcinoma, rectal adenocarcinoma, lung adenocarcinoma andlung squamous cell carcinoma samples." (PMID 21559523, 2011). "A cluster of 13 CpG loci (11 genes) were identified that displayed differential methylation in colon adenocarcinoma (COAD) (N = 289) compared to normal colon tissues (N = 38): ZNF671, TWIST1 (two CpG loci), TMEFF2, TM6SF1, GAS7, MAL, HIN1 (two CpG loci; SCGB3A1), COL6A2, AKR1B1, GPX7, ARHGEF7)." (PMID 34903270, 2021).
metastatic disease (2 papers, 2015 to 2019). "Based on the results suggesting that loss of TMEFF2 often predates aggressive/metastatic disease, we postulated that the TMEFF2-modulated TMCC11 gene signature could have prognostic value." (PMID 31060542, 2019). "In clinical samples from the Grasso and MSKCC datasets, the expression of the individual genes from the TMCC11 signature is significantly increased in CRPC and metastatic disease samples when compared to normal tissue, and inversely correlated with the expression of TMEFF2 in the same samples." (PMID 31060542, 2019).
prostate tumors (2 papers, 2019 to 2022). "Our data in six types of cancers showed overexpression of TMEFF2 in prostate tumors only, suggesting that this protein is not involved in tumorigenesis of highly aggressive cancers and that its expression could negatively control aggressiveness." (PMID 35565454, 2022).
rectal cancer (2 papers, 2011 to 2016). A primary or metastatic malignant neoplasm that affects the rectum. "Ten of the 36 (EYA4, FOXI2, CNRIP1, SFRP1, ADHFE1, C2orf40, MAL, PHACTR3, SST, TMEFF2) were known as rectal cancer related genes with aberrant methylation." (PMID 27566576, 2016). "Ofthe seven tumor types where these data are currently available, onlyglioblastoma, and occasionally ovarian and rectal cancer samples showsignificant levels of TMEFF2 expression." (PMID 21559523, 2011).